CD4 (CD4 molecule)
Diseases named in the same sentence as CD4 in open-access papers (continued):
Sharing a sentence is not in itself a finding about the gene and the disease.
viral infection (continued). "In conclusion, our data show for the first time that monocytes and CD4 cells are sensitive biosensors to monitor type I interferon response signatures in autoimmunity and viral infection and how these transriptional responses are modulated in a cell- and disease-specific manner." (PMID 24391825, 2013). "While fate determination of CD4 T cells has been extensively studied in case of acute infections, the following section will specifically focus on the differentiation of CD4 T cells during active chronic viral infections." (PMID 23717308, 2013). "The expression of CCR6 influences migration of memory CD4+ T-cell subsets into the intestine, brain, and other tissues, and may contribute disseminating viral infection." (PMID 24009735, 2013). "Interestingly, differences in the cortical actin between naïve and memory CD4+ T cells affecting viral DNA synthesis have been recently reported in cell-free virus infections." (PMID 24244453, 2013). "The demonstration of a role of the cortical actin in HIV cell-to-cell transfer and infection of memory and naive CD4+ T cells may provide a mechanistic understanding of viral infection and pathogenesis." (PMID 24244453, 2013). "However, compared with the administration of Ad:null 90 days post viral infection, the administration of Ad-IL-17AR:Fc decreased the percentage of CD4+ Th17+ T cells." (PMID 23977238, 2013). "However, following virus infection only IL-4Rα was notably differentially regulated on certain immune cell subsets (i.e. CD4+ T cells, CD8+ T cells and DCs)." (PMID 23383283, 2013). "Therefore, it can be assumed that monocytes, as the foot soldiers of the innate immune system, are the more sensitive biosensors in detecting viral infections compared to CD4+ T cells." (PMID 24391825, 2013). "Therefore, it is most likely that these cells play an important role in the development of anti-viral CD4+ T cell responses in the CNS during the early stage of viral infection." (PMID 22985464, 2012). "SAMHD1-mediated HIV-1 restriction in myeloid cells and resting CD4+ T-cells is likely a general mechanism to protect host cells from productive viral infection, which can also be a potential strategy of HIV-1 immune evasion to avoid efficient anti-viral innate immunity." (PMID 23092163, 2012). "We negatively sorted CD4+ T cells from chronically HIV infected subjects and infected the cells with a primary HIV virus ((US1/GS 004(91US-1)-CCR5 HIV-NIH AIDS Research and Reference Reagent Program) since the levels of endogenous virus infection of autologous CD4+ target cells is <1%." (PMID 22792231, 2012). "Indeed, these animals have been extensively used to delineate the role of CD4+ T cells in AdV and other viral infections or tumor models." (PMID 23071696, 2012). "To directly test the capacity for CB2R activation to inhibit viral infection, we pretreated activated CD4+ T cells with a potent and selective CB2R agonist that is approximately 200-fold selective for CB2R over CB1R (Ki = 3.4 nM) (JWH-133) prior to HIV-1 exposure." (PMID 22448282, 2012). "Both CD4+ and CD8+ T-cells responses in C3 deficient mice are decreased in viral infection models." (PMID 22973398, 2012). "This phenomenon was explained by the hypothesis that sCD4 can efficiently replace cell-surface CD4 to drive virus infection in CD4-negative and CCR5-positive cells." (PMID 23217195, 2012). "Despite any such enhanced CKR cell surface topography that might facilitate CD4-independent viral infection of transiently Leu3a treated cells, CD4 dependence increased progressively with successive passages, and became nearly absolute by P24." (PMID 22830620, 2012). "Inter-DC antigen transfer has been reported to result in tolerance induction in CD4+ T cells in the steady state, while in the context of a viral infection it may lead to amplified CD8+ immune responses." (PMID 22649530, 2012). "R5 virus infection in all three subtypes correlated with higher CD4+ count." (PMID 22281097, 2012).
viral infection (continued). "Recent data from immunization studies using the efficacious smallpox and yellow fever vaccines have shown that induction of specific polyfunctional CD4+ or CD8+ T cells may play a role in protective immunity." (PMID 21347287, 2011). "In our model, changes in naïve CD4 and CD8 T cells are mediated in trans; we hypothesize that the remaining changes found in memory CD4 T cells are mediated in cis by viral infection." (PMID 22043290, 2011). "Interestingly immune activation between V38E and WT virus infection was similar even though CD4 decline was limited in V38E infection." (PMID 21255440, 2011). "Although it has been proposed that this rapid and dramatic loss of intestinal CD4+ T cells is due to the high proportion of “activated” memory CD4+ T cells expressing CCR5 which are more permissive of viral infection, the mechanisms by which these cells are eliminated remain controversial." (PMID 22096538, 2011). "Although we would like to have examined integration directly using the Alu-LTR qPCR assay as we performed in our previous study, the sensitivity of this assay is not amenable to the measurement of integration products with non VSV-G pseudotyped virus infections using HeLa CD4+ cells." (PMID 21682883, 2011). "These ligands may also serve as effective adjuvants in viral diseases and conjugates of antigen-anti-dectin-1 mAb can be used to induce CD4+, CD8+ T and B cell responses against viral infections." (PMID 20976143, 2010). "A number of studies on persistent murine and human viral infections indicate that virus specific CD4+ T cells play a critical role in the outcome of viral infections, and are required to maintain effective cytotoxic T cell responses and neutralizing antibodies." (PMID 21151917, 2010). "We found that, HIV-infected patients with CD4+ cell counts of around 200 cells/mm3 are less likely to be infected with any virus examined here suggesting that a higherCD4+ cell count does play a role in immunity against virus infection." (PMID 20604948, 2010). "Soluble forms of the CD4 receptor and small molecules that mimic the effects of CD4 can inhibit virus infection; however, how this inhibition occurs is still unknown." (PMID 19343205, 2009). "CD4+ T cells play an important role in the immune response against viral infections." (PMID 21994541, 2009). "A low CD4+/CD8+ ratio can flag viral infection, classically HIV, and has been reported in IP." (PMID 19941660, 2009). "HIV infection depletes a broad profile of leukocyte subsets including many that do not express CD4 and are not susceptible to direct virus infection." (PMID 19832988, 2009). "To exclude such variables from our system and to expand our analysis of the contribution of different DC subsets to viral infection, we took advantage of the availability of HA-specific CD4+ and CD8+ T cells to probe antigen presentation in influenza virus in BALB/c mice in vivo." (PMID 18301768, 2008). "Intra-nasal immunization with N SRS was specifically associated with the presence of CD4+CD69+ lymphocytes as early as 4 days and up to 10 days after virus infection, as compared with non vaccinated or LT(R192G) immunized mice where CD8+CD69+ lymphocytes were the predominant subset." (PMID 18335041, 2008). "Indeed, virus infection is spreading to the CD4+ T-cell population at later time points and the ATP-directed modification of virus production decreased with time." (PMID 18373845, 2008). "In addition to CD4+ T cells, other cell types, such as innate lymphoid cells, natural killer cells, and mast cells, including neutrophils, can also be sources of IL-17 after viral infection." (PMID 40006915, 2025). "In terms of infections, as CD38 is expressed at the surface of activated CD4+T cells, this study cannot rule out that daratumumab might have played a role in predisposing patients to infections, such as pneumocystis or viral infections." (PMID 40467580, 2025).
viral infection (continued). "Viral infections are known to induce CD4+ and CD8+ T-cell activation, which in combination with drug exposure may lead to excessive infiltration of inflammatory T-cells into the skin, resulting in increased production of cytokines such as interleukin (IL)-8 and IL-36." (PMID 40125151, 2025). "However, Th1 CD4+ T cell responses also induce the activation of B cells that secret opsonizing antibodies that are able to mark infected cells for killing during an active viral infection." (PMID 40733639, 2025). "Thus, a stable and defined minimal bacterial consortium is able to shape the immune response to a systemic virus infection via enhancing effector cell function of CD4+ T helper cells including cytotoxic T cell subsets and viral clearance at the cost of enhanced disease pathology." (PMID 40274773, 2025). "In the case of viral infections, an increased abundance of CD4+CD27-CD28+ cells may be an early indicator of the prioritized loss of CD27 in CD4+ T cells, with the eventual loss of the CD28 antigen as cells progress to a differentiated state, in contrast with CD8+ T cells." (PMID 38502582, 2024). "It is postulated that viral infection could trigger CD8 T-cell hyperactivation and increased antibody production to compensate for this deficient CD4 T-cell response in genetically predisposed individuals (HLA-DR15), which may lead to autoimmune hypophysitis or direct pituitary damage." (PMID 39044822, 2024). "Thus, intranasal boosting immunization can substantially promote airway CD45+ and CD4+CD44+ T lymphocyte accumulation which may act immediately upon virus infection." (PMID 38987276, 2024). "To investigate whether the protein expression of Integrin α4 correlates with the RNA expression changes in different CD4 T cell populations, including TFH and TH1 cells, we utilized adoptive transfer of antigen-specific CD4 T cells in an acute virus infection mouse model." (PMID 39720725, 2024). "Notably, increases in the percentage of CD4+CCR4+ T cells are commonly found in inflammatory diseases, and the finding here is consistent with our previous results indicating that p12KO virus infection is associated with a higher inflammatory profile." (PMID 38668247, 2024). "Cytotoxic CD4+ T cells have been reported to have critical effector functions in the context of several pathologies, such as in the elimination of melanoma tumor cells, in the protection against hepatocellular carcinoma, and in the control of several viral infections (90, –, 92)." (PMID 37656815, 2023). "However, it was shown that IL-9 could modulate CD4+ responses in some viral infections, including respiratory syncytial virus infection and coxsackievirus B3-induced myocarditis." (PMID 37649897, 2023). "The pattern of antiviral gene expression in brain parenchymal CD4 T cells closely resembled that observed for CD4 and monocyte/macrophage clusters in the spleen, suggesting that CD4 T cells in both compartments exhibited similar biological responses to viral infection." (PMID 38060615, 2023). "Common viral infections in children (i.e. adenovirus, SARS-CoV-2, and parainfluenza virus) were associated with a slight increase in CD38+ HLA-DR+ T cells compared with children in the healthy control group (P = 0.04 for CD4+T cells and P = 0.10 for CD8+T cells)." (PMID 37751296, 2023). "Also, effective immunogens against viral infections should trigger cellular and humoral responses, while T CD4+ cells stimulate antibody production and sustain the effector functions of CTLs, which induces clearance of infected cells through inflammatory mediators." (PMID 38115107, 2023). "Functional annotation analysis of the significantly DEGs detected at DPI 2 vs. control in the CD4+ subset revealed that the biological processes (BP) enriched in our dataset of upregulated genes mostly related to innate immune responses and host defense against viral infection." (PMID 37243138, 2023).
viral infection (continued). "Thus, both cell types that propagate viral infection are potential targets for CD4+ CTL." (PMID 37965314, 2023). "Interestingly, B and CD4+ T cells were elevated in children with BMI above the age norm in this study, possibly reflecting insufficient function of B- and T- cells in resolution of viral infection." (PMID 37234860, 2023). "Thus, the delayed induction of CD4+ T cell responses to either vaccination or even viral infection could be a predictive factor for compromised immune responses." (PMID 37118516, 2023). "By killing target cells, CD4 CTLs under pathologic conditions, which exhibit upregulated cytotoxic and proinflammatory molecules (e.g., granzyme, perforin, interferon-γ, etc.), are able to control tumor growth and viral infection as well as hasten the progression of autoimmune diseases." (PMID 36737819, 2023). "We may not have seen a robust increase in TCF1/7− TOX+ EOMES+ CD8+ T cells in young CD4-depleted mice because our model is an acute viral infection while other studies used CD4 depletion as a syngergistic approach along with a cancer or chronic infection model to promote CD8+ T cell exhaustion." (PMID 37528458, 2023). "For example, higher rates of virus infection were observed upon administration of the Fc variants of bNAbs (e.g. anti-CD4bs 3BNC117 and anti-V3 glycan PGT121) with diminished versus intact Fc functions to reporter mice transduced to express human CD4 and CCR5 receptors and challenged with HIV-1." (PMID 34986207, 2022). "Although we have focused on LCMV viral infection, this study represents the first step into building a more comprehensive reference map of the transcriptional landscape supporting the functional heterogeneity of CD4+ T cells across tissues and beyond viral infections." (PMID 35829695, 2022). "In addition to the possibility of direct viral infection, hypersomnia after COVID might be related to immune and inflammatory hyperactivation resulting in hypothalamic infiltration by CD4+ and CD8+ T cells leading to neuronal damage." (PMID 36352367, 2022). "However, whether additional heterogeneity exists amongst the CD4+ T cell pool during chronic viral infection remains unclear." (PMID 36255051, 2022). "Notably, recent studies have identified that a memory-like CD4+ T cell population develops alongside Th1 and Tfh cell subsets during chronic viral infection and that this memory-like subset bears a strikingly similar transcriptional profile as Tcmp cells from acute LCMV infection." (PMID 36255051, 2022). "Circulating CD4+ T cells possess a range of helper and effector functions, and they are important for the control of different types of innate and adaptive immune effector mechanisms, as well as the clearance of almost all viral infections, including SARS-CoV-2." (PMID 35337103, 2022). "It had been reported that continuous immune responses against viral infection led to the loss of CD8+ memory T-cell diversity, while other studies showed that thymic involution might initiate accumulation of specific dysregulated CD4+ T cells." (PMID 36159829, 2022). "Thus, CD4+ T cells play a key role for the establishment of long-term cellular and humoral antigen-specific immunity, which is the basis of life-long protection for many viral infections and vaccines." (PMID 36679862, 2022). "It has been reported that genes related to cytotoxicity, such as Granzymes, NKG7, and IL18RAP, are upregulated in CD4+ CTLs in a mouse viral infection model, similar to what we saw in the present study, suggesting that these genes are generally induced in CD4+ CTLs upon viral infections." (PMID 36077655, 2022). "While the mechanisms involved remain the subject of future studies, we speculate that this induction of CD4 expression on Vδ2 T cells may be a general inflammatory event in the host, triggered during some viral infections, a phenomenon which has also been noted to occur during COVID-19 infection." (PMID 35669780, 2022).
viral infection (continued). "Thus, CD4+ T cell differentiation during acute viral infection is a well-synchronized process that results in appropriately balanced Th1, Tfh, and Tcmp cell formation at the peak of infection, and these subsets can then give rise to highly functional memory populations." (PMID 36255051, 2022). "Following viral infection in mammals, IFNy is produced early and transiently by activated NK cells (though other lymphoid cells also produce the cytokine), and afterwards predominantly by CD4+ and CD8+ T cells once these have been activated by exposure to antigen." (PMID 33671162, 2021). "The cross-reactive CD4+ T cells might not be implicated solely in terminating the virus infection however they may limit the virus burden and reduce the course of symptomatic infection leading to lower incidences of severe disease." (PMID 33777028, 2021). "To investigate this theory, we assessed a number of baseline immune factors, including CD4+ T cells, T helper 17 (Th17) and T regulatory (Treg) cells in the colon, that we hypothesized could influence acute viral infection and potentially affect the virological response to ART and outcome of ATI." (PMID 34138927, 2021). "Previous studies demonstrated similar transcriptional features of tumor-infiltrating CD8+ T cells to those of cells with chronic virus infection, implying that CD4+ T cells may also show similar transcriptional responses to the tumor and chronic virus infection." (PMID 33598101, 2021). "Thus, they inhibit autologous CD4 T cell proliferation in autoimmunity; and in viral infections to avoid an excessive inflammatory response that might be lethal to the host." (PMID 34685542, 2021). "Given that CD4+ T cells could indirectly modulate virus infection by orchestrating antibody production, enhanced T-cell-mediated immune responses, as shown in W4P-RBD vaccination, can contribute to the production and maintenance of IgG and IgA antibodies with potent neutralizing activity." (PMID 33732258, 2021). "In contrast, FoxP3+CD4+ T cells may be beneficial in controlling acute viral infections." (PMID 34067536, 2021). "In association with other viral infections such as cytomegalovirus (CMV) or human immunodeficiency virus (HIV), increased numbers of CD8+ cytotoxic suppressor T-cells have been reported, in line with our findings of an increased CD8 cell count resulting in a reduced CD4/CD8 ratio." (PMID 32272749, 2020). "In addition to CAR4 T cells exhibiting direct control of in vitro HIV replication, we reasoned that they could also restore CD4+ T cell help that is lost as a consequence of viral infection." (PMID 32454027, 2020). "Even though not all people living with HIV are immunocompromised, especially those under ART with an undetectable HIV viral and normal CD4 count, these people may still be vulnerable to viral infection or subsequent bacterial pneumonia than the general population." (PMID 32703286, 2020). "Therefore, the roles of smoking and virus infection in CD4+ and CD20+ cell recruitment into the bronchial mucosa remain unclear." (PMID 32283204, 2020). "Moreover, lovastatin did not significantly affect MHC-I or CD4 expression in Nef-deficient viral infection." (PMID 31572371, 2019). "However, linc-GALMD1 was not identified in F1 generation chickens and its expression was decreased in CD4+ T cells after viral infection in line 63 chickens, implying linc-GALMD1 might involve suppressing the chicken MD." (PMID 31798630, 2019). "We used a conditional mouse Oct1 (Pou2f1) allele and a CD4-Cre driver to determine the effect of T cell-specific Oct1 loss on autoimmune- and viral-induced neuroinflammation using an autoantigen-driven EAE model of autoimmunity and a JHMV model of viral infection." (PMID 31266507, 2019). "However, it remains unclear why AE-specific CD8 T cells exhibited greater cytotoxicity toward target CD4 T cells while promoting DC maturation to fuel viral infection." (PMID 31398241, 2019).